INS (insulin)
Diseases named in the same sentence as INS in open-access papers (continued):
Sharing a sentence is not in itself a finding about the gene and the disease.
diabetes (continued). "Additionally, insulin’s ability to modulate inflammation and oxidative stress in clinical settings adds to its cardiovascular benefits, making it a valuable component of diabetes management." (PMID 39125938, 2024). "Identifying that a patient is currently taking insulin for diabetes." (PMID 38587879, 2024). "Diabetes mellitus is a debilitating disease characterized by elevated blood glucose levels due to insufficient insulin production by pancreatic beta cells or insulin resistance in specific organs and tissues responsible for removing excess glucose from the blood." (PMID 39696686, 2024). "Based on the findings, it can be concluded that the bioactive secondary metabolites present in PK have the potential to treat diabetes and dyslipidemia through various mechanisms, such as increasing insulin secretion, inhibiting intestinal alpha-glucosidase, and activating glucokinase." (PMID 39334723, 2024). "In addition to its antiatherogenic properties, HDL has the latent capability to improve glycemic control in mouse models of diabetes by boosting pancreatic β-cell function and increasing insulin sensitivity (Manandhar, Cochran & Rye, 2020)." (PMID 39421410, 2024). "Materials and Methods: A total of 200 patients (59.5 ± 9.1 year old, 151 male) with type 2 diabetes mellitus treated with metformin were randomized to insulin (n = 50 served as controls), liraglutide (n = 50), empagliflozin (n = 50) or their combination (liraglutide + empagliflozin) (n = 50)." (PMID 38541121, 2024). "Glucose is essential for the functioning of virtually all organs, therefore, disturbances in the synthesis or secretion of insulin may contribute to the development of many diseases, including insulin resistance and diabetes." (PMID 38250713, 2024). "Notably, Apigenin has been reported to inhibit α-glucosidase activity, enhance insulin secretion, and neutralize reactive oxygen species, potentially preventing diabetes complications." (PMID 39201257, 2024). "Additionally, no group differences were identified for either parent–adolescent communication subscale according to adolescent gender, family history of diabetes, blood glucose monitoring technique or insulin administration modality." (PMID 37386763, 2024). "Multiple regression analysis was adjusted sequentially for Mode 1 (gender, age, BMI, duration of diabetes, hypertension, smoking history, and drinking history), Mode 2 (Mode 1 and HbA1c, fasting C-peptide, fasting insulin, and eGFR), and Mode 3 (Mode 2 and Ca2+, Mg2+, PTH, and serum lipids)." (PMID 38904033, 2024). "Most cases of this type of diabetes require daily insulin treatment over the long term." (PMID 38686201, 2024). "Expanding on previous findings, this study examined the role of endothelial cell-specific NOX5 expression in an STZ-induced insulin-deficient diabetes mouse model in the presence or absence of NOX4 expression." (PMID 38671844, 2024). "The ALIVE project of the European Society of Veterinary Endocrinology defines diabetes mellitus as a heterogeneous group of diseases with multiple etiologies characterized by hyperglycemia resulting from inadequate insulin secretion, inadequate insulin action, or both." (PMID 38539988, 2024). "Many studies have indicated that flavonoids may help manage diabetes by improving insulin sensitivity and reducing inflammation, making them valuable in the management of this chronic condition." (PMID 39199168, 2024). "Diabetes mellitus (DM) is marked by insulin resistance and impaired glucose metabolism, primarily in the liver, leading to reduced insulin sensitivity, diminished hepatic glycogen synthesis, and inhibited gluconeogenesis, which exacerbates glucose and lipid dysregulation." (PMID 39459158, 2024). "The paper "Using Absorption Models for Insulin and Carbohydrates and Deep Leaning to Improve Glucose Level Predictions" (Sensors2021, 21, 5273) proposes a novel approach to predicting blood glucose levels for people with type 1 diabetes mellitus (T1DM)." (PMID 39001139, 2024).
diabetes (continued). "The association between FG and SMI is not independent of the use of anti-diabetes medication and insulin, as the adjustment for the use of anti-diabetes medication and insulin attenuated the association." (PMID 38637769, 2024). "Unadjusted linear regression analyses demonstrated that higher cfPWV (as a continuous variable) was associated with longer diabetes duration, higher age, HbA1c (current and retrospective), MAP and liver stiffness, and lower time-in-range and lower insulin sensitivity." (PMID 40302945, 2024). "These individuals may in fact have the most to gain from automating insulin delivery and reducing diabetes burden." (PMID 38932805, 2024). "In the context of diabetes, neutrophils primarily release inflammatory molecules that affect blood vessel integrity, and monocytes discharge various hormones and cytokines influencing insulin secretion and function." (PMID 39075586, 2024). "According to a study, diabetes mellitus could potentially affect breast density in DBT through the insulin signaling pathway." (PMID 38536577, 2024). "“I had to ration my insulin and diabetes supplies when I was uninsured and underinsured." (PMID 38711747, 2024). "As long-term insulin resistance could lead to beta cell dysfunction, there is a need to know the prevalence of low insulin production in patients with long-term diabetes mellitus." (PMID 38654804, 2024). "Consequently, this study concluded that a 12-week structured exercise training program effectively improves insulin resistance, quality of life, functional capacity, and glycaemic control in individuals with type 2 diabetes mellitus." (PMID 38771888, 2024). "Furthermore, specific subsets of β-cells have been identified in diabetes, such as displaying an immature, dedifferentiated gene signature, expressing significantly lower insulin mRNA levels, and expressing increased β-cell precursor markers." (PMID 38731945, 2024). "Diabetes mellitus is a chronic metabolic disorder characterised by hyperglycaemia, which is caused by a lack of insulin, insulin insufficiency and/or insulin resistance." (PMID 39595804, 2024). "Consequently, conducting a comprehensive comparison of insulin pumps is essential in assisting doctors, healthcare professionals, and patients with diabetes when selecting the most suitable equipment for their specific needs." (PMID 39065641, 2024). "Although glucose regulation often becomes inadequate with these options as the disease progresses, there is some degree of “clinical inertia” due to the complexity and fear of insulin therapy, both from the perspectives of healthcare providers and people with diabetes." (PMID 38672255, 2024). "In diabetes management, glucose-responsive NPs facilitate smart insulin delivery." (PMID 39458672, 2024). "Ultimately, it is expected that combining glucose sensing and insulin delivery in a single insertion device may reduce the burden of care and ultimately improve the lives of people living with diabetes." (PMID 38491800, 2024). "For severe insulin-deficient diabetes relative to mild diabetes, the relative risks for using insulin relative to no common treatment would be expected to increase by a factor of 3.07 (95% CI 2.73, 3.44), holding other factors constant." (PMID 38625583, 2024). "Average diabetes duration was ~ 6 years and 9% were receiving insulin." (PMID 38932889, 2024). "Diabetes can be classified into type 1 and type 2: diabetes type 1 is caused by a lack of insulin secretion by beta cells of the pancreas, while diabetes type 2 is caused by a deceased sensitivity of target tissues to insulin." (PMID 38256225, 2024). "However, one constant is that sex plays a critical and very complex role in glucose metabolism, affecting insulin sensitivity, β cell mass and its resilience to diabetes, and insulin synthesis and release." (PMID 38358819, 2024).
diabetes (continued). "Thus, strategies for treatment of diabetes have generally been focused on increasing the sensitivity of target tissues to insulin, on increasing the function of existing/remaining pancreatic β-cells, or on replacement of β-cells." (PMID 39290144, 2024). "The results indicated that pancreatic β-cell function and stimulation levels were retained at 12 months in the FMT group, suggesting that FMT can protect pancreatic β-cell function in patients with diabetes diagnosed 12 months after onset and avoid a drop in endogenous insulin production." (PMID 38660489, 2024). "We reviewed their medical history to determine the nature of their diabetes management, identifying whether they controlled their condition through diet (n = 14, 13.1%), oral medication (n = 62, 57.9%), or insulin ± oral medication (n = 31, 29.0%)." (PMID 39457536, 2024). "However, a significant proportion of individuals with diabetes struggle to consistently follow their prescribed insulin regimens, interrupting or discontinuing insulin treatment shortly after initiation." (PMID 38610878, 2024). "Furthermore, the monoterpene myrcene has been studied for its role in improving glucose tolerance and insulin sensitivity, suggesting potential benefits in diabetes management." (PMID 39070783, 2024). "Diabetes mellitus was divided by treatment: diet alone, oral therapy, and insulin therapy." (PMID 38392602, 2024). "Early identification of vulnerable refugees and asylum seekers, prompt intervention with access to insulin and other essential diabetes medications, appropriate monitoring and trained healthcare providers must be standard in any humanitarian response and integrated into routine care." (PMID 39063405, 2024). "It is speculated that it plays a role in preventing diabetes by affecting insulin signaling, inhibiting fibrosis, and enhancing antioxidation." (PMID 39682788, 2024). "Potential reasons for this phenomenon could be that the use of insulin may be a marker for diabetes severity indicating insulin resistance and high glycemic burden." (PMID 38952394, 2024). "One patient was diagnosed with diabetes mellitus and treated with insulin and metformin." (PMID 38780650, 2024). "Therefore, glimepiride was discontinued, and diabetes treatment was converted to vildagliptin 100 mg/day and insulin glargine 3 units/day." (PMID 39247010, 2024). "A previous study showed that only 53% of commune health centers (CHCs) offered diabetes services, with only 3% having at least one type of diabetes medication (metformin, glibenclamide, or insulin), while 64% of CHCs offered treatment services for cardiovascular diseases." (PMID 38166740, 2024). "Data from the Diabetes Collaborative Registry (2013–2016) showed that metformin, sulfonylureas, and insulin were used more by patients with type 2 diabetes compared to SGLT2-is and GLP-1 RAs, which were used by only 4.2% and 5.5% respectively by DM patients in the registry." (PMID 36378394, 2024). "However, access to a practice diabetes nurse increased the chances of timely basal insulin-initiation." (PMID 38116986, 2024). "The Indonesian Association of Endocrinologist publishing guidelines on diabetes treatment provides no specific explanation on the selection and superiority of insulin types (analogue vs human insulin)." (PMID 39361609, 2024). "Interestingly, we also observed that gene functions in subgroup 1 and 2 were related to diabetes mellitus and insulin signaling pathway, which indicated their potential regulations in PDAC progression through mediating diabetes and insulin signaling pathways." (PMID 38827297, 2024). "Diabetes and stroke might have been reported more accurately if respondents required insulin or had experienced a defined medical event, such as a stroke." (PMID 38115171, 2024).
diabetes (continued). "In this framework, the gut microbiota could be considered a central player, influencing obesity through its effects on weight regulation, diabetes through its influence on insulin sensitivity, and cancer through its involvement in chronic inflammation." (PMID 39459519, 2024). "In the context of diabetes management among the patient population, the data revealed that 56% (N=26) of patients took oral tablets to control their diabetes, while 44.4% (N=20) used insulin as their treatment method." (PMID 39781130, 2024). "If the same mechanisms can be confirmed, aspects of insulin secretion and glucose effectiveness may be elucidated, potentially contributing to the treatment of diabetes." (PMID 38731926, 2024). "The role of automated insulin delivery systems in diabetes is expanding." (PMID 38740602, 2024). "In addition, obesity and diabetes promote metabolic changes in lipids, carbohydrates, insulin resistance, altered activity of adipocyte hormones, disrupted micronutrient metabolism, and elevated oxidative stress." (PMID 38583985, 2024). "PTMs of insulin can also increase autoimmune reactions in diabetes." (PMID 38540730, 2024). "In addition to an obvious increase in weight and body mass index (BMI), obese subjects were significantly younger and more frequently presented diabetes, sleep apnea and liver steatosis while displaying significantly higher levels of insulin and HOMA-IR." (PMID 39334798, 2024). "Increased insulin exposure due to insulin resistance or even insulin administration in patients with diabetes may contribute to carcinogenesis through the upregulation of IGF-I activity or downregulation of IGF-binding protein-1 activity." (PMID 38902745, 2024). "Likewise, the intestinal microbiota (IM) is essential in regulating glucose, insulin, and triglycerides related to pathogenesis and treating metabolic diseases such as obesity and diabetes." (PMID 39727642, 2024). "Various strategies such as adopting a healthy diet, using hypoglycemic agents, and administering insulin have been implemented for diabetes management, but most conventional medicines have some undesirable side effects and this often contributes to diabetic treatment failure." (PMID 38383908, 2024). "10% of all adults with diabetes were using insulin within one year of diabetes diagnosis." (PMID 39060948, 2024). "Another mechanism affecting blood vessels involves insulin resistance, increasing cardiovascular risk even without a diagnosis of diabetes." (PMID 38813430, 2024). "He gave the name to the eponymous Somogyi effect or Somogyi hypothesis (in short, rebound hyperglycemia after insulin-induced hypoglycemia, particularly nocturnal), which was an axiom in the treatment of diabetes for decades." (PMID 39718705, 2024). "Beta cells are critical to diabetes by producing insulin to control blood glucose levels." (PMID 38516378, 2024). "The FDC of MSP could be a good armamentarium for physicians to manage Indian patients with T2DM characterized by insulin resistance that is not controlled by dual therapy, as well as for those with uncontrolled diabetes who are reluctant to take insulin." (PMID 38336931, 2024). "In this nationwide cross-sectional population-based study, we found that PWD were significantly more likely to participate in DSME if they had a medium or high level of education, had type 1 diabetes, were receiving insulin treatment, and had diabetes for more than five years." (PMID 39264968, 2024). "However, in individuals with diabetes, muscle and other cells become resistant to insulin, resulting in persistently high blood-sugar levels." (PMID 38791732, 2024).
diabetes (continued). "Therefore, in the clinic, C-peptide is often a more reliable alternative to insulin for assessing β-cell activity and diagnosing diabetes status since C-peptide is generally found in the bloodstream in approximately equal proportions to insulin." (PMID 38540150, 2024). "Among these, renal failure, postoperative coma, extracardiac arteriopathy, age, prolonged ventilation, reoperation for bleeding, and insulin-treated diabetes emerged as the major predictors for survival in stroke patients compared with non-stroke patients in the past year." (PMID 38392602, 2024). "The reduction in BDNF-impaired hippocampal long-term potentiation (LTP) is responsible for cognitive functions and insulin sensitivity, which may lead to diabetes." (PMID 39664526, 2024). "In addition, absence of storage facilities for insulin explained the shortage of insulin for diabetes in one of the regional referral hospitals in Hoima3." (PMID 38553700, 2024). "Thus, age-related changes of skeletal muscles related to aging lead to impaired blood glucose control, increased insulin resistance, and the development of diabetes." (PMID 38612998, 2024). "Compared with the other two groups, those with definite CAN were more likely to have an Aboriginal background, to be diagnosed with diabetes at a younger age and to have longer diabetes duration, to be obese, and to have a higher HbA1c despite a greater likelihood of insulin therapy." (PMID 38500197, 2024). "Disorder of CDC42, can prevent healthy insulin secretion and promote diabetes." (PMID 39160196, 2024). "Similarly, data from the Swedish population revealed that copeptin level can be used as a predictor of development of diabetes, independently of other loading factors, including fasting glucose and insulin and family history of diabetes mellitus." (PMID 39769071, 2024). "Additionally, interference in Wnt signaling pathways is involved in the development of diabetes, as it affects the proliferation and differentiation of pancreatic β-cells and the secretion of insulin." (PMID 38674437, 2024). "Taken together, the results indicate that adverse effects induced by insulin use may shorten the lifespan in individuals with diabetes." (PMID 38592103, 2024). "Among them, age, gender, ethnicity, weight, height, BMI, smoking history, HbA1c, SBP, eGFR, DBP, HDL, LDL, total cholesterol, triglyceride, use of insulin, duration of diabetes, and family history of diabetes CVD are determined as the persistent features in the prediction of CoDM." (PMID 38178670, 2024). "Diabetes was a chronic hyperglycemic disease that occurred when the pancreas failed to produce sufficient insulin or when the body was unable to effectively utilize the insulin it produced." (PMID 39737158, 2024). "Therefore, the study provides evidence that structured SMBG has a positive impact on glycaemic control among insulin-treated outpatient diabetes clinic patients in northeastern Tanzania." (PMID 38899147, 2024). "In mice, α-cells and δ-cells can transform into insulin-producing β-cells after β-cell ablation, aiding in diabetes recovery, but whether this occurs in humans is unclear." (PMID 39057094, 2024). "Diabetes is a chronic metabolic disorder marked by abnormal blood glucose levels (BGLs), resulting from either insufficient insulin production or the ineffective use of insulin by the body." (PMID 39065913, 2024). "Both RAIAs and long-acting insulin analogs are prescribed for effective diabetes management." (PMID 39457586, 2024). "Despite an array of modern glucose, lipid and blood pressure drugs and technologies such as insulin pumps and continuous glucose monitors, many people with diabetes develop chronic complications, such as diabetic retinopathy, nephropathy and cardiovascular disease, including cardiomyopathy." (PMID 38397785, 2024).